MMP9 (matrix metallopeptidase 9)
Diseases named in the same sentence as MMP9 in open-access papers (continued):
Sharing a sentence is not in itself a finding about the gene and the disease.
tumor (continued). "Examination of tumor specimens from our case series showed that miR-18a high ER+ tumors had a dense lymphocyte infiltrate when compared to miR-18a low tumors but expressed a higher CD4/CD8 ratio and the M2 macrophage marker CD206, along with the invasive marker MMP9." (PMID 35626709, 2022). "However, at present, the expression of MMP9 and cisplatin sensitivity in SCLC patients has not been clarified and the associated relationship with the tumor immune microenvironment is not clear." (PMID 35431936, 2022). "MMP9, which degrades major extracellular structures and releases various signal peptides, is involved in tumor growth and metastasis by regulating epithelial-mesenchymal transition (EMT), stimulating tumor cell survival and invasion in response to TNF-α-induced inflammatory signals." (PMID 36555705, 2022). "MMP-2 and MMP-9, also known as gelatinases, have been long recognized as major contributors to the proteolytic degradation of ECM during tumor invasion, which are responsible for mediating the degradation of different components of the ECM, the shackle for tumor." (PMID 35929837, 2022). "Therefore, we speculate that the high expression levels of MMP2 and MMP9 promote EMT in MRTK, thus promoting tumour migration and invasion and leading to malignant tumour progression." (PMID 36408277, 2022). "Moreover, HCC tumor cells were found to induce the conversion of HSCs into CAFs through the secretion of miR-21, which promoted cancer progression via the secretion of the angiogenic factors VEGF, MMP2, MMP9, bFGF and TGF-β." (PMID 35158892, 2022). "In this study, the results showed that CCL25/CCR9 could increase the expression of MMP2 and MMP9 by activating PI3K/AKT in SACC, which was confirmed in xenograft tumor mice, suggesting that CCL25/CCR9-activated PI3K/AKT might modulate MMPs through the transcription factor SLUG." (PMID 36003306, 2022). "The acidification of tumoral environments produces favorable conditions for tumor cell invasion, as it induces the formation and maturation of invadopodia and activates proteases to focally degrade the ECM, through metalloproteinase 3 activity and MMP9 secretion." (PMID 36076905, 2022). "The change of MMP9 suggests that OL could inhibit the invasion and metastasis of SCCHN tumor cells." (PMID 36050634, 2022). "Therefore, we hypothesized that there may be a crucial regulatory relationship between SATB1 and MMP-9 and EMT during the formation of tumor growth, metastasis and chemoradioresistance in NPC." (PMID 33390772, 2021). "The CCL5/CCR5 pathway also supports tumour cell invasion by activating downstream pathways such as PI3K/AKT and calcium/calmodulin-dependent protein kinase II (CaMKII) that ultimately result in the production of matrix metalloproteinase-2 (MMP-2) and -9 (MMP-9)." (PMID 33803414, 2021). "Although MMP-9 and MMP-2 are mostly similar substrates, it is hypothesized that they are regulated by different mediators, expressed under different conditions, and therefore have different instances in which they affect the tumor micro-environment." (PMID 32172480, 2021). "MMP9 plays an important role in ECM remodeling, which could promote tumor metastasis." (PMID 33574243, 2021). "The reduction in MMP-9 was restricted to only metastatic tissue but not tumor tissue." (PMID 34202203, 2021). "Thus, new therapeutic strategies are focusing on inhibitors that can prevent the binding of MMPs to cell surface receptors, such as, for instance, a synthetic peptide that blocks the MMP9 PEX domain leading to decreased cell migration of HT-1080 and MDA-MB-435 tumor cells." (PMID 34066419, 2021). "Notably, treatment with either cromolyn or levetiracetam blunted MMP9 production by MCs in vivo, but it did not affect MMP9 expression in T23 tumor cells." (PMID 33737929, 2021).
tumor (continued). "In addition, impaired MMP7, MMP9, and ADAM9 expression were found in ALOC-EO-treated B16F10 cells in a dose-dependent manner in vitro indicating that ALOC-EO suppresses the expression of tumor cell-derived proteases." (PMID 34360915, 2021). "Furthermore, CypA knockdown activated caspase-3, a critical executioner of apoptosis, and suppressed the expression of matrix metalloproteinase (MMP)-9 and MMP-2 that play an important role in tumor invasion and metastasis, consistent with the effect of compound 9 treatment in our previous study." (PMID 33804393, 2021). "Moreover, the expression levels of the CAT, ESR1, and KLKB1 genes were significantly correlated with the HCC stage (P < 0.05), while MMP9 was not significantly correlated with the tumor stage." (PMID 34671598, 2021). "Additionally, through Western blotting, we investigated the effect of NLSPE5 on the expression of N- cadherin and E-cadherin and the matrix metalloproteinases MMP-2 and MMP-9 in MDA-MB-231 cells, which are involved in the migratory and invasive capacities of tumor cells." (PMID 34503160, 2021). "The involvement of the TNF-α and MMP-9/TIMP-1 complex in radiation-induced non-targeted effects led to the inhibition of tumor angiogenesis, highlighted by the 0.34-fold decrease in the MMP-9/TIMP-1 ratio in patients without AIT, which was only 0.8-fold in patients with coexisting AIT." (PMID 34298820, 2021). "Moreover, matrix metalloproteinase 9 (MMP9) and neutrophil elastase (NE) secrete by TANs, through the degradation of extracellular matrix (ECM) components, contribute to VEGF release, which in turn promotes tumor vascularization and invasion." (PMID 34885122, 2021). "Moreover, metastasis and tumor-induced angiogenesis of malignant tumor cells were suppressed by inhibiting the production of MMP-9 and pro-angiogenic factors in in vitro and in vivo, with no apparent side effects." (PMID 33801741, 2021). "MMP2 (log2 fold change = 7.47), MMP9 (log2 fold change = 3.63), and TIMP2 (log2 fold change = 2.66) displayed increased expression in the TME, while MMP13 (log2 fold change = −4.41) and TIMP1 (log2 fold change = −2.26) displayed increased expression in the HCC tumor." (PMID 33995488, 2021). "Our finding that multiple signaling pathways are involved in the inhibition of MMP-9 by TGF-β (and possibly stimulation by PMA and other growth factors) has expanded our knowledge on the regulation of this important molecule involved in tumor invasion and metastasis." (PMID 34769032, 2021). "In renal carcinoma, tumor-derived EVs contained elevated levels of multiple miRNAs including miR-19b, miR-29c, and miR-151 and significantly enhanced the expression of pro-PMN genes in lung endothelial cells, including the pro-angiogenic VEGFR1, VEGF, and MMP9." (PMID 34943937, 2021). "TGF-β also enhances tumor invasiveness and angiogenesis by promoting the production and secretion of matrix metalloproteases proteinase-2 (MMP-2) and matrix metalloproteinase-2 (MMP-9) and downregulating the expression of tissue inhibitors of metalloproteases (TIMP)." (PMID 34335834, 2021). "Among MMPs, matrix metalloproteinase 9 (MMP-9), the main proteolytic enzyme of MMPs involved in metastasis formation, can degrade various protein components in the extracellular matrix (ECM), disrupt the histological barrier of tumor cell invasion, and result in acceleration of tumor metastasis." (PMID 33828938, 2021). "MMP-9 and VEGF are involved in tumor cell invasion and metastasis, and curcumin-mediated inhibition of human tongue squamous carcinoma CAL-27 cells invasion may be partly attributed to the downregulation of NF-kB and its downstream target genes such as MMP-9 and VEGF." (PMID 33578780, 2021). "At the same time, VOSO4 did not exert any effect on MMP-9/MMP-2 expression in tumour cells." (PMID 33670389, 2021).
tumor (continued). "We found that in addition to KLF4 and BMI1, miR-135a also inhibited the expression of MMP2 and MMP9, as shown by Western blot, and inhibited MMP activation, as shown by the decrease in the intensity of MMPSense in FMT, which plays important roles in promoting tumor invasion and metastasis." (PMID 33828977, 2021). "Elemene reduced metastatic tumor nodules in a mouse metastasis model constructed with SGC7901/ADR cells and reduced the expression of miR-1323, Cbl-b, and E-cadherin in the lungs of nude mice, whereas vimentin, MMP-2, and MMP-9 were significantly downregulated." (PMID 34641334, 2021). "On the one hand, tumor-associated neutrophils (TANs) may contribute to local hypoxia via respiratory burst-dependent oxygen expenditure; on the other hand, HIF1 regulates neutrophil functions and may promote neutrophil expression of pro-tumor factors, such as TNF-alpha, VEGFA, and MMP9." (PMID 33810575, 2021). "The anti-tumor “N1” phenotype exhibited increased tumor cytotoxicity, elevated expression of CXCL13, CCL3, CCL6, CXCL10, TNFα and ICAM-1 and low ARG1 content, while the pro-tumor “N2” neutrophils expressed high levels of ARG1, MMP9, VEGF and several cytokines, including CCL2, CCL5, CCL17 and CXCL4." (PMID 34572138, 2021). "Interestingly, tumor ECs from metastatic tumors showed a higher invasive potential than tumor ECs from non-metastatic tumors, and this has been linked with higher expression levels of gelatinase/collagenase IV, MMP-2 and MMP-9." (PMID 34073394, 2021). "In light of these data, Ezrin represents a key regulator of tumor metastasis progression for its ability to regulate cell migration promoting EMT and to enhance the invasion capability through up-regulation MMP-2 and MMP-9 transcriptional and translational levels via the AKT signalling pathway." (PMID 33003361, 2020). "The negative correlation between DLC1 and MMP9 expression in a relatively low percentage of cases could be due to the great heterogeneity between tumor samples that may harbor other genetic and/or epigenetic factors to alter the regulatory relationship between DLC1/FOXK1 and MMP9." (PMID 32214200, 2020). "Furthermore, EDW01 displayed MT1-MMP and MMP-13 at the tumour-stromal boundary, but did not express these factors or MMP-2 and MMP-9 within the tumour mass itself." (PMID 33276802, 2020). "In addition, these specific anti-tumor actions of Calebin A further correlated with inhibition of cell metastatic (CXCR4, MMP-9) and proliferative (cyclin D1) biomarkers, all of which are known to have a NF-κB binding site in their promoters, thus promoting their transcription." (PMID 32708030, 2020). "Breast cancer cells direct the tumor angiogenesis via pro-angiogenic factors such as interleukin-1 (IL-1), interleukin-8 (IL-8), vascular endothelial growth factor (VEGF), basic fibroblast growth factor (bFGF), tumor necrosis factor α (TNFα) and matrix metalloproteinases 9 (MMP9)." (PMID 32012744, 2020). "In addition, we found that the number of neutrophils continuously increased, and these cells expressed high levels of Mmp9, Prok2, Vegfa, and Nos2, but not tumor suppressors." (PMID 32709844, 2020). "The absence of MMP-9 function reduced the angiogenic switching and the growth of tumor cells." (PMID 33343560, 2020). "Acting on different substrates, the outcome of MMPs is a balance between pro-angiogenic and anti-angiogenic effects; for instance, MMP-9 can also generate the angiogenic and tumor repressor tumstatin, a fragment including the noncollagenous domain (NC1) of collagen alpha-3 (IV)." (PMID 32456248, 2020). "At the same time, tumor hypoxia triggers the hypoxia-inducible transcription factor (HIF)-1, which, in turn, promotes MMP-9 expression either directly or by activating the expression of growth factors, inflammatory cytokines or chemokines which are able to promote MMP-9 expression." (PMID 32630531, 2020).
tumor (continued). "Whilst not a marker of stemness, MMP9 is linked with EMT as it plays a key role in degradation of the extracellular matrix and therefore by aiding the escape of epithelial tumor cells from their location of origin, MMP9 expression has been linked to the metastatic potential of HCC cells." (PMID 32374744, 2020). "This study also showed that fucoidan-related MMP-9 expression was mediated by activator protein (AP)-1 and NF-κB binding activity, and that treatment with wortmannin, a PI3K-specific inhibitor, abolished tumor suppressive effects by regulating MMP-9, NF-κB, and AP-1 in fucoidan-treated cells." (PMID 33333858, 2020). "Moreover, expression of ZEBRA by tumor cells from NPC patients correlates with advanced lymph node metastasis, and this effect has been related to direct transactivation of the Matrix Metalloproteinase (MMP9) promoter by ZEBRA." (PMID 32517128, 2020). "MMP-9 expression in NSCLC could be helpful to predict prognosis and evaluate the tumor grades." (PMID 32944046, 2020). "Indeed, in our study, we found that migratory and invasive abilities were increased in tumour spheres, compared to parental A549 cells; expression levels of N‐cadherin, vimentin, MMP‐9 and MMP‐1 were also increased in tumour spheres, compared to parental A549 cells." (PMID 32396269, 2020). "We could see that about half MMPs are highly expressed in tumor tissues as compared with normal tissues, including MMP9, MMP10, MMP11, MMP12, MMP15, MMP25, MMP26 (all, P<0.05), while some other MMPs decreased in tumor tissues, including MMP2, MMP14, MMP16, MMP24, MMP28(all, P<0.05)." (PMID 32669958, 2020). "There are studies that have not shown the MMP-9 expression in healthy tissue surrounding tumor." (PMID 31143300, 2019). "In our study, although S100A4-dependent MMP-9 expression was inhibited by BITC treatment in vivo, S100A4/MMP-9 could not exert its inhibitory effect on tumor metastasis, which might be due to changes in the environment inside the tumor." (PMID 30970087, 2019). "MMP-2, MMP-9, and uPA are thought to play important roles in the degradation of ECM proteins, which is a key factor in tumor metastasis and invasion, and inhibition of their protein expressions and proteolytic activities can be an important strategy to prevent tumor metastasis and invasion." (PMID 31783709, 2019). "This can likely be attributed to the absence of tumour progression steps leading to metastasis in subcutaneous xenografts, and to possible differences in the desmoplastic reaction between the two models that affect the efficacy of anti‐MMP9 stromal targeting." (PMID 30941918, 2019). "This suggests that these myeloid cells are a predominant cell type that secretes MMP9 into the MMTV-PyMT metastatic niche, although other cells, including myeloid, stromal, and/or tumor cells, may also be a source of MMP9 and contribute to metastatic colonization." (PMID 31727800, 2019). "Moreover, immunohistochemical analysis suggested that the slower tumor growth rate and the reduced metastasis by miR-25 inhibition were, at least in part, due to the upregulation of LATS2 and E-cadherin expression and the downregulation of Vimentin and MMP9." (PMID 31316723, 2019). "Moreover, tumor cell metastasis related gene products, such as VEGF, MMP-9, and ICAM-1, could be mitigated by FCN." (PMID 31466313, 2019). "MMPs as a family of zinc-dependent proteolytic enzymes include MMP-1, MMP-3, and MMP-9, have the ability to degrade collagen and other ECM proteins, and play a crucial role in different pathophysiology conditions, such as invasion, vascular remodeling, angiogenesis, and tumor metastasis." (PMID 31762729, 2019).
tumor (continued). "Tumour tissues from these subcutaneous xenografts revealed low but detectable levels of MMP9 protein in all therapy groups without any significant difference in MMP9 expression." (PMID 30941918, 2019). "Moreover, we found that MMP-9 expression was upregulated in tumor tissues compared with the paired adjacent non-tumor tissues (P < 0.001)." (PMID 31293204, 2019). "We also demonstrated the anti-tumor mechanism by which GXI could induce HepG2 apoptosis via the mitochondrial pathway and had the ability to inhibit HepG2 cell migration by downregulating the expression of MMP-7 and MMP-9." (PMID 31569691, 2019). "MMP-9 and TIMP-1 expression in the normal mucous adjacent to the tumor might be an effect of the activity of neoplastic cells and their interaction with the adjacent environment as well as inflammatory cell intrusion, which was shown in more than half of the studied specimens." (PMID 31143300, 2019). "The expressing levels of MMP‐9 and TGF‐β in the IHC assays, displayed as the distribution and intensity of the positive signals, seem not to be related with the onset ages and tumour sizes of the diseased dogs, but show close association with the tumour malignancy." (PMID 31264317, 2019). "MMP-9 may act as an angiogenic switch due to its ability to increase the bioavailability of angiogenic factors including VEGF, which is the most potent mediator of tumor vasculature." (PMID 31817718, 2019). "In addition, activated MDSCs in tumours could affect tumour remodelling and tumour angiogenesis by producing VEGF, basic fibroblast growth factor (bFGF), Bv8 and MMP9, thereby promoting tumour progression." (PMID 31462297, 2019). "Indeed, a recent investigation revealed that SPOCK1-promoted tumor growth and metastasis are accompanied by upregulation of MMP-3 and MMP-9 expressions in PCa, suggesting that MMPs may be involved in the SPOCK1-mediated EMT process and subsequent metastasis." (PMID 31182131, 2019). "In CCL9-expressing CMT93 colon carcinoma, CCR1+ neutrophils secrete MMP9 to foster cancer foci, and in late phases of tumor the neutrophils recruit fibrocytes or induce differentiation from monocytes to fibrocytes which secrete MMP2, accommodating tumor cell colonization." (PMID 31474975, 2019). "CO2 also significantly inhibits tumor growth, tumor new blood vessel formation, and cancer cell invasion by affecting the expression of hypoxia-inducible factor 1-alpha (HIF-1a), vascular endothelial growth factor (VEGF), matrix metalloproteinase-2 (MMP-2), and matrix metalloproteinase-9 (MMP-9)." (PMID 30845750, 2019). "Though reports are conflicting on whether some PIs affect cell proliferation, indinavir has been reported to affect MMP-2 and MMP-9, but not p21, which emphasizes its importance in tumor metastasis, rather than initiation, specifically." (PMID 31687607, 2019). "Interestingly, although incubation of EOC cells in culture with rFBLN5 did not inhibit tumor cell MMP-9 (not shown), rFBLN5 inhibited adhesion of EOC cells to specific matrix components." (PMID 29581841, 2018). "Moreover, MMP-9 can distinguish the extent of invasiveness regardless of tumor types, size and status (primary or recurrent), paving the way of MMP-9 to clinical practice." (PMID 32922863, 2018). "We corroborated that MMP-9 cleaves and inactivates key T-cell chemoattractant CXCR3 ligands (CXCL9, CXCL10, and CXCL11) in vitro, and that anti-MMP-9 treatment may contribute to tumor T-cell homing/trafficking via stabilization of CXCL10 in vivo." (PMID 30500835, 2018). "Matrix metallopeptidase 9 (MMP-9) is a collagenase responsible for the degradation of type IV collagen, the major component of the basement membrane, and other essential extra cellular matrix components, being involved in the tumor cell invasion and metastasis." (PMID 30352460, 2018). "Nonetheless, this result does not rule out the possibility that FBLN5 may suppress MMP-9 generated in tumor stroma or macrophages." (PMID 29581841, 2018).